GSTP1 (glutathione S-transferase pi 1)
Diseases named in the same sentence as GSTP1 in open-access papers (continued):
Sharing a sentence is not in itself a finding about the gene and the disease.
pancreatic cancer (12 papers, 2007 to 2025). "Beyond its classical detoxification function, GSTP1 has been implicated in tumorigenicity, oxidative stress protection, and cell cycle regulation in pancreatic cancer." (PMID 40719618, 2025). "Variant alleles of GSTP1 have also been correlated with heightened risks of pancreatic cancer." (PMID 40290119, 2025). "However, the precise mechanisms underlying GSTP1's role in promoting pancreatic cancer cell growth and proliferation remain unclear." (PMID 40719618, 2025). "The first study to suggest a role of GSTP1 polymorphisms in pancreatic pathogenesis concluded that genetic polymorphisms of GSTP1 may be among the mechanisms that modify the risk of pancreatic cancer in older individuals and affect the survival of patients who receive 5-fluorouracil-based treatment." (PMID 31357662, 2019). "Pancreatic cancer is a multifactorial disease with metastasis-prone and therapy-resistant nature; the predominant expression of GSTP1-1 in pancreatic cells may explain why GSTP1 polymorphisms exerted effects on risk and survival of pancreatic cancer." (PMID 31357662, 2019). "In the context of pancreatic cancer, we demonstrate that GSTP1 is essential for cancer cell survival, as evidenced by the significant reduction in proliferation across PDAC cell lines following its knockdown." (PMID 40719618, 2025). "Taken together, our data suggest that GSTP1 is a potential and promising novel therapeutic target to treat pancreatic cancer patients." (PMID 32526885, 2020). "In this present study, we provide evidence suggesting that GSTP1 contributes to pancreatic cancer cell growth and holds promise as a therapeutic target for PDAC." (PMID 32526885, 2020). "Our findings are an important first step towards the validation of GSTP1 as a novel therapeutic target to treat pancreatic cancer patients." (PMID 32526885, 2020). "Intriguingly, we show that GSTP1 is present at higher levels in pancreatic carcinoma cell lines (MIA PaCa-2, PANC-1, HPAF-II, AsPC-1, and BxPC-3) compared to normal Human Pancreatic Nestin-Expressing ductal cells (hTERT-HPNE)." (PMID 32526885, 2020). "Furthermore, in an orthotopic pancreatic cancer mouse model, GSTP1 knockdown tumors showed an impressive reduction in growth compared to control tumors." (PMID 32526885, 2020). "Interestingly, they found that pancreatic cancer cell growth was particularly sensitive to GSTP1 knockdown." (PMID 32526885, 2020). "While SNPs in the phase I and II metabolism genes CYP1A1, GSTM1, GSTT1 and GSTP1 alone did not correlate with pancreatic cancer risk, a significant interaction between smoking and the GSTT1 null genotype was reported in Caucasian pancreatic cancer subjects." (PMID 24651674, 2014). "The interplay between GSTP1, DDAH1 and PDIA6 highlights the complexity of redox regulation in pancreatic cancer and suggests that targeting GSTP1 may offer a new therapeutic approach for PDAC." (PMID 40719618, 2025). "Indeed, tumor expression of GSTP1 does not predict the safety or efficacy of platinum-based chemotherapy regimen Folfirinox (leucovorin, fluorouracil, irinotecan, and oxaliplatin) in patients with pancreatic cancer." (PMID 31357662, 2019).
esophageal cancer (11 papers, 2006 to 2024). A primary or metastatic malignant neoplasm involving the esophagus. "GSTP1 gene has been associated with various cancers, including breast, lung, prostate, bladder, and esophageal cancer." (PMID 28212552, 2017). "Finally, GSTP1 is a major GST isoform expressed in the human esophagus but a review on the argument stated that results of relations between GSTP1 polymorphisms and esophageal cancer were inconsistent." (PMID 31357662, 2019). "Some genes like GSTP1 was related with ESCC in the South African population; high CYP3A5 activity could increase esophageal cancer risk in Black Africans." (PMID 28410201, 2017).
Obesity (11 papers, 2008 to 2025). Accumulation of substantial excess body fat. "GSTP1 rs1695 is associated with increased risk of obesity and cardiometabolic abnormalities in young adults from Brazil; individuals carrying at least one G allele have a 2.4 times higher chance of being obese compared to those with the A/A genotype." (PMID 40732231, 2025). "The dominant model of inheritance showed an association between rs1695 in GSTP1 and obesity (OR: 0.42, 95% CI: 0.20–0.87; p = 0.018)." (PMID 40732231, 2025). "Conversely, we demonstrated an association between rs1695*G GSTP1 and obesity (OR: 0.42; 95% CI: 0.20–0.87; p = 0.018) in a dominant inheritance model in patients receiving SGAs." (PMID 40732231, 2025). "In contrast, an association of rs1695*G GSTP1 with obesity (OR: 0.42; 95% CI: 0.20–0.87; p = 0.018) was shown in the dominant model of inheritance in patients receiving second-generation antipsychotics." (PMID 40732231, 2025). "Individuals who carry less efficient alleles of detoxification enzymes GSTP1 are subject to lower production or inefficient activity of these detoxification enzymes, which favours the development of obesity." (PMID 38703299, 2024). "GSTT1 deficiency, > 2 hr/day of SHS exposure, and obesity were each independently associated with lower TP and LF, and there was a trend toward an association of GSTP1 (Ile105Val) with TP." (PMID 19057702, 2008). "Interestingly, patients who have taken SGAs for an extended period have shown associations between rs1695 in GSTP1 and obesity." (PMID 40732231, 2025). "Moreover, a positive correlation between GSTP1 polymorphism and obesity was observed on young adults with obesity, revealing its significant role in the increase of susceptibility of obesity and cardiovascular risk in this population." (PMID 38703299, 2024). "To analyze the oxidative imbalance linked to obesity detected at the plasma level, we evaluated two important cytoplasmatic antioxidant enzymes, SOD1 and GSTP1, in adipose tissue." (PMID 33255520, 2020). "We found significant two-way interactions for the effect of high SHS exposure and GSTM1, GSTT1, GSTP1, and obesity on TP." (PMID 19057702, 2008). "The SAPADIA cohort team previously reported on the modifying effect of antioxidative GST gene polymorphisms (GSTM1 and GSTT1 gene deletions and the GSTP1 SNP Ile105Val) in the association of HRV with the inflammatory risk factors second-hand smoke and obesity in the general population." (PMID 25133672, 2014). "In addition, for LF, two-way interactions were also significant for GSTT1, GSTP1, and obesity." (PMID 19057702, 2008). "In contrast, the abundance of GSTP1 was decreased in platelets from patients with obesity compared to individuals without obesity, which may also increase the production of oxidative agents and pro-inflammatory mediator in some cases." (PMID 38703299, 2024).
benign prostatic hyperplasia (10 papers, 2007 to 2025). A non-cancerous nodular enlargement of the prostate gland. "The optimised method which was developed in this study evaluates DNA methylation changes of RASSF1A and GSTP1 in the blood of PCa patients at different stages compared to benign prostatic hyperplasia patients and healthy individuals." (PMID 34503269, 2021). "The method was used to identify promoter hypermethylation of 2 tumour suppressor genes RASSF1A and GSTP1 in the circulating cell-free DNA (cfDNA) from serum samples of PCa patients (n = 75), benign prostatic hyperplasia (BPH, n = 58), and healthy individuals (controls, n = 155)." (PMID 34503269, 2021). "Thanks to its capacity for staining in basal cell layer, we hypothesized that GSTP1 could be used to discriminate benign prostatic hyperplasia and PIN (which maintains basal cell staining uniformity) from PCa (which lacks a basal layer)." (PMID 27594734, 2016). "Although hypermethylation of GSTP1 is rarely detected in normal prostate or benign prostatic hyperplasia (BPH), it is hypermethylated in >90% of cancers and about 70% of precursor high grade intraepithelial neoplasia (PIN) lesions." (PMID 20671914, 2010). "The results were evaluated in comparison to the GSTP1 and RASSF1A methylation status of healthy individuals (n = 155) as well as benign prostatic hyperplasia (BPH, n = 58) patients." (PMID 34503269, 2021). "Methylation of the GSTP1 gene promoter has been the most frequently detected epigenetic alteration, and occurs in over 90% of cancerous samples and about 70% of prostatic intraepithelial neoplasia (PIN) samples, but is rarely detected in normal prostate or benign prostatic hyperplasia (BPH) tissues." (PMID 22547956, 2011). "The most promising methylation biomarker identified to date is glutathione-S-transferase pi (GSTP1), detected in >90% of prostate tumours, >70% of HGPIN and at significantly lower frequencies and quantitatively much lower levels in normal prostate and benign prostatic hyperplasia (BPH)." (PMID 17453001, 2007).
prostatic intraepithelial neoplasia (10 papers, 2004 to 2025). "GSTP1 is highly expressed in basal cell layer and luminal cells in benign glands while in prostatic intraepithelial neoplasia (PIN) it stains only basal cell layer, whereas PCa glands are completely negative." (PMID 27594734, 2016). "In the course of PCa, the origin of GSTP1 hypermethylation has been traced to late preneoplastic stages like high-grade prostatic intraepithelial neoplasia and proliferative inflammatory atrophy lesions." (PMID 15292941, 2004). "We put special emphasis on GSTP1, because its methylation has been shown to occur early in high-grade prostatic intraepithelial neoplasia (HGPIN), suggesting the possibility of using GSTP1 to detect very early stage of recurrence." (PMID 24086370, 2013). "The progression from inflammation to preneoplastic lesions, such as high-grade prostatic intraepithelial neoplasia (PIN), and eventually to prostate cancer (PC) may be influenced by the methylation of the GSTP1 gene." (PMID 39891849, 2025). "A possible drawback is the high frequency of GSTP1 methylation in patients with high-grade prostatic intraepithelial neoplasia (HG PIN) and in patients with negative or suspicious PB." (PMID 23774836, 2013). "Loss of GSTP1 function may contribute to the early stages of PCa development, with GSTP1 methylation evident in 5–10% of proliferative inflammatory atrophy (PIA) precursor lesions, and 70% of high-grade prostatic intraepithelial neoplasia (PIN) lesions, respectively." (PMID 25389438, 2014).
cervical carcinoma (9 papers, 2009 to 2023). A carcinoma arising from either the exocervical squamous epithelium or the endocervical glandular epithelium. "GSTP1 has been associated with tumor promotion and drug resistance in breast, colon, and cervical cancers." (PMID 32526885, 2020). "GSTP1 overexpression is associated with resistance to chemotherapeutic drugs like cisplatin, carboplatin, adriamycin, and bleomycin in ovarian and cervical cancer." (PMID 32526885, 2020). "The inhibitory effects of GSTP1-1 on TRAF2 were shown in human cervical cancer cells, where overexpression of GSTP1-1 suppressed TRAF2-induced activation of both JNK and p38." (PMID 37189435, 2023). "Human cervical cancer HeLa cells overexpressing GSTP1 suppress TRAF2-induced activation of both JNK and p38." (PMID 33946704, 2021). "With its established roles in breast and cervical cancer, we postulate that overexpression of GSTP1 provides selective advantages to PDAC cells by scavenging elevated ROS and maintaining cellular homeostasis." (PMID 32526885, 2020). "In support of this, ERK and NF-κB protein expression were reduced in cervical cancer cells upon GSTP1 inhibition." (PMID 32526885, 2020). "Our data are supported by a previous report that suggested GSTP1 knockdown elevated phosphorylated JNK expression in cervical cancer cells." (PMID 32526885, 2020). "Similar results were observed when GSTP1 was inhibited using specific morpholinos in cervical cancer." (PMID 32526885, 2020). "Hence, we suggest GSTM3 and GSTP1 as novel biomarkers and potential therapeutic targets for treating cervical cancer." (PMID 29774096, 2018). "Further, GSTP1 knockdown in pancreatic and GSTM knockdown in cervical cancer cells showed reduced phosphorylation of extracellular signal-regulated kinase (ERK1/2),which plays a pivotal role in promoting cell growth and proliferation in many mammalian cell types." (PMID 33946704, 2021). "Moreover, GSTM3 and GSTP1 are involved in cell survival and proliferation in cervical cancer cell lines, but information is not available regarding their function in GBM." (PMID 34209254, 2021). "In addition, using an anti-HPV-16 E7 antibody we immunoprecipitated HPV-16 E7 in the CaSki and SiHa cervical carcinoma cell lines, known to express HPV-16 E7 endogenously, GSTP1 also co-precipitated with the viral oncoprotein in these cells, as detected by Western blot analysis." (PMID 19826491, 2009).
chronic obstructive pulmonary disease (9 papers, 2007 to 2025). A chronic and progressive lung disorder characterized by the loss of elasticity of the bronchial tree and the air sacs, destruction of the air sacs wall, thickening of the bronchial wall, and mucous accumulation in the bronchial tree. "The rs1695 SNP of the GSTP1 gene has been studied in the general population of Croatia to investigate its association with Alzheimer disease, chronic obstructive pulmonary disease, and multiple sclerosis." (PMID 35505645, 2022). "GSTP1 mutations have also been linked to chronic obstructive pulmonary disease, a disease with clear etiologic connections to PH." (PMID 34669463, 2021). "Besides, genetic polymorphisms of GSTP1 may be associated with chronic obstructive pulmonary disease (COPD) development suggesting GSTP1-Val allele to be more protective." (PMID 34988113, 2021). "Silencing GSTP1 in patients with chronic obstructive pulmonary disease (COPD) increases reactive oxygen species (ROS) production and DNA damage in cells." (PMID 33599104, 2021).
head and neck cancer (9 papers, 2012 to 2026). A primary or metastatic malignant neoplasm affecting the head and neck. "It has been shown that the GSTP1*T/T genotype is likely to be related to overall cancer susceptibility among the Asian and African population and specifically, colorectal and head and neck cancers in the Caucasian population." (PMID 32183092, 2020). "The authors were unable to identify a positive association between the GSTP1 rs1695 A/G polymorphism and the risk of overall head and neck cancer." (PMID 30665373, 2019). "The Glutathione S-transferase P1 (GSTP1) polymorphism have been considered a risk modifier for developing head and neck cancer (HNC) in many studies; however, the results of such studies are inconsistent." (PMID 23144854, 2012). "However, this association was confirmed for the GSTP1-313 A/G + G/G genotypes polymorphism, where at least one polymorphic allele present confers reduced risk for head and neck cancer." (PMID 32592358, 2020). "Third, GSTP1 may influence susceptibility to head and neck cancer independently or with other genes." (PMID 23144854, 2012). "Moreover, the TT genotype of GSTP1 rs1138272 may be associated with the risk of head and neck cancer in the overall population." (PMID 30740061, 2018). "A cost-minimization analysis was planned to compare GSTP1 c.313A>G genotyping versus overall fosaprepitant implementation for patients with head and neck cancer under chemoradiation therapy with high-dose cisplatin." (PMID 30870506, 2019). "Although we observed a potential relationship between GSTP1 rs1138272 and the risk of colorectal, lung, head and neck cancers within Caucasians, no more than 10 case-control studies were enrolled, and more detailed head and neck cancer types were not evaluated due to the lack of sufficient data." (PMID 30740061, 2018).
lymphoma (9 papers, 2006 to 2021). A malignant (clonal) proliferation of B- lymphocytes or T- lymphocytes which involves the lymph nodes, bone marrow and/or extranodal sites. "Less active polymorphisms of GSTP1 confer less resistance to lymphoma development." (PMID 17026765, 2006). "Different polymorphisms of GSTP1 have been associated with the development of lymphoma, suggesting that GSTP1 may be important in the development and/or progression of lymphoma in humans." (PMID 17026765, 2006). "For example, EA improves the antitumor effects of arsenic trioxide (ATO) in myeloid leukemia and lymphoma cells by inducing apoptosis and inhibiting GSTP1-1." (PMID 27487128, 2016). "Some studies indicated that GSTP1-1 had an inhibitory impact on the As2O3 activity in lymphoma cells." (PMID 26569224, 2015). "A correlation between promoter hyper-methylation of GSTP1 and response to chemotherapy in diffuse large B-cell lymphoma proving that GSTP1 gene methylation status could be an indicator of drug response and a prognosticator for this lymphoma." (PMID 31357662, 2019).